PAK6 (p21 (RAC1) activated kinase 6)
Diseases named in the same sentence as PAK6 in open-access papers (continued):
Sharing a sentence is not in itself a finding about the gene and the disease.
colon carcinoma (8 papers, 2014 to 2022). "In line with our observation, PAK6 was reported to be associated with overall survival, enhancing chemotherapeutic resistance and was proposed as a prognostic marker for colon cancer patients." (PMID 34885088, 2021). "In conclusion, our study indicates that PAK6 decreases 5-FU drug susceptibility in colon cancer cells and is an independent prognostic factor for adjuvant 5-FU-based chemotherapy in patients with stage II and stage III colon cancer." (PMID 25426562, 2015). "Our results showed that downregulation of PAK6 resulted in a higher overall survival probability in colon cancer patients." (PMID 34885088, 2021). "These in vivo data are consistent with the in vitro results, and confirm that PAK6 overexpression promotes colon cancer progress and 5-FU chemoresistance." (PMID 25426562, 2015). "All of these results indicate that PAK6 has the potential to predict 5-FU-susceptibility in patients with stage II and stage III colon cancer." (PMID 25426562, 2015). "This is the first report showing evidence for PAK6 playing a critical role in colon cancer pathogenesis and chemoresistance." (PMID 25426562, 2015). "In this study, we used quantitative real-time polymerase chain reaction (qPCR), western blotting, and immunohistochemistry (IHC) to assess PAK6 expression, and found that it was markedly increased in colon cancer tissues relative to normal colon epithelium." (PMID 25426562, 2015). "In summary, our results indicate that a combination of PAK6 inhibition and 5-FU treatment results in significantly decreased survival in colon cancer cells, which can be restored by PAK6 expression." (PMID 25426562, 2015). "We used the Kaplan-Meier analysis to show that the expression of PAK6 was significantly correlated with the disease-free survival (DFS) of colon cancer patients (log-rank test, P < 0.001)." (PMID 25426562, 2015). "Further validation by IHC showed that PAK6 protein was localized to the cytoplasm of cancer cells, and 104 of 147 (70.75%) primary colon cancers showed positive staining; only 9 of 147 (6.12%) normal colonic epithelium were immunoreactive for PAK6." (PMID 25426562, 2015). "Here we report that in colon cancer PAK6 promotes tumor progression and chemoresistance both in vitro and in vivo." (PMID 25426562, 2015). "We have further evaluated PAK6 as a predictor of 5-fluorouracil (5-FU) treatment response in colon cancer." (PMID 25426562, 2015). "Collectively, our novel clinical and mechanistic data demonstrate that increased PAK6 expression confers a more aggressive phenotype and resistance to 5-FU-based chemotherapy in colon cancer." (PMID 25426562, 2015). "We observed that the level of PAK6 expression was closely correlated with tumor differentiation (P = 0.002) and recurrence (P < 0.001) in colon cancer patients." (PMID 25426562, 2015). "Of the 40 randomly selected paired cases that were used to evaluate PAK6 mRNA and protein expression, 26 (65%) colon cancers had at least a 2-fold increase in PAK6 mRNA levels compared to the adjacent noncancerous tissues." (PMID 25426562, 2015). "To investigate the role of PAK6 in mediating sensitivity to colon cancer chemotherapy, we used 2 human colon cancer cell lines, HCT8 and HCT116." (PMID 25426562, 2015). "In the present study, we initially measured PAK6 expression in fresh frozen colon cancer specimens and found that PAK6 mRNA and protein levels were higher in colon tumor tissues than in the surrounding noncancerous mucosa." (PMID 25426562, 2015). "P21-activated kinase 6 (PAK6) plays an important role in colon cancer." (PMID 36213507, 2022). "Moreover, down-regulating the expression of PAK6 is an effective strategy in inhibiting the migration and invasion of colon cancer cells." (PMID 34113558, 2021). "Moreover, transduction of colon cancer cells with PAK6 shRNA resulted in cellular arrest in G2-M stage, a more chemosensitive stage of the cell cycle." (PMID 25426562, 2015).
colon carcinoma (continued). "In this study, it was shown that in colon cancer cells, PAK6 inhibition significantly increased the extent of 5-FU induced apoptosis and increasing PAK6 protein expression decreased apoptosis, supporting the notion that PAK6 plays a role in apoptosis evasion." (PMID 25426562, 2015). "Taken together, these findings indicate that PAK6 may protect colon cancer cells from 5-FU induced apoptosis." (PMID 25426562, 2015). "To clarify the functional role of PAK6 in chemotherapy, we used an shRNA-based strategy to stably downregulate PAK6 in colon cancer cells that express high levels of the protein, and overexpressed PAK6 in colon cancer cells that express low levels of the protein." (PMID 25426562, 2015). "This suggests that at the time of an initial colon cancer diagnosis, PAK6 expression might be used to not only identify the optimal individualized treatment, but also to distinguish patients who are more likely to benefit from chemotherapy after surgery." (PMID 25426562, 2015). "Furthermore, for stage II and III colon cancer patients, high PAK6 expression was an independent prognostic factor for OS (P < 0.001) and DFS (P < 0.001)." (PMID 25426562, 2015). "Colon cancer cell lines showed increased PAK6 expression upon 5-FU treatment." (PMID 25426562, 2015). "The aim of this study was to evaluate whether PAK6 can influence 5-FU-based chemotherapeutic sensitivity in colon cancer cells, and determine whether PAK6 expression is a useful marker for guiding 5-FU adjuvant therapy after curative resection of colon cancer." (PMID 25426562, 2015). "Furthermore, the presented mechanistic evidence strongly suggests that dysregulated PAK6 expression confers 5-FU chemoresistance in colon cancer cells." (PMID 25426562, 2015). "The data presented support the hypothesis that PAK6 could serve as a prognostic indicator of colon cancer outcome in patients with stage II and III disease treated with 5-FU-based adjuvant chemotherapy following curative surgery." (PMID 25426562, 2015). "Finally, we were able to confirm the role of PAK6 in colon cancer progression in animal models." (PMID 25426562, 2015). "However, in colon cancer patients who receive adjuvant chemotherapy after tumor resection, the role of PAK6 remains unclear." (PMID 25426562, 2015). "Collectively, these data indicate that PAK6 may be involved in colon cancer progression." (PMID 25426562, 2015). "This study demonstrates that PAK6 is an independent prognostic factor for adjuvant 5-FU-based chemotherapy in patients with stage II and stage III colon cancer." (PMID 25426562, 2015). "Subsequent western blotting confirmed that the level of PAK6 protein was also higher in the colon cancer samples than in the matched adjacent non-tumor tissues." (PMID 25426562, 2015). "We found that PAK6 was dramatically upregulated in 104 of 147 (70.75%) primary colon cancer patients specimens, but was either absent or only minimally expressed 9 of 147 (6.12%) in the adjacent normal colonic tissue." (PMID 25426562, 2015).
Parkinson disease (7 papers, 2020 to 2026). A progressive degenerative disorder of the central nervous system characterized by loss of dopamine producing neurons in the substantia nigra and the presence of Lewy bodies in the substantia nigra and locus coeruleus. "The aberrant activation of PAK6 in the striata of patients with LRRK2-linked Parkinson’s disease supports the role of PAK6 in the pathogenesis of Parkinson’s disease." (PMID 33306168, 2022). "Our previous work uncovered a link between PAK6 and the Parkinson’s disease (PD)-associated kinase LRRK2, with PAK6 controlling LRRK2 activity and subcellular localization via phosphorylation of 14–3–3 proteins." (PMID 39419978, 2024). "Moreover, PAK6 can bind to LRRK2 (leucine-rich repeat kinase 2), which is a cause of Parkinson’s disease, and is required for LRRK2 to regulate neurite outgrowth." (PMID 33306168, 2022). "Besides, PAK6 controls neurite complexity in the healthy brain and leucine-rich repeat kinase 2 (LRRK2), a causative gene for Parkinson’s disease (PD)." (PMID 33796531, 2021).
cervical cancer (6 papers, 2021 to 2025). A primary or metastatic malignant neoplasm involving the cervix. "In cervical cancer, PAK6 has been demonstrated to activate the Wnt/β‐catenin signalling pathway and promote cell growth." (PMID 39233332, 2024).
gastric cancer (6 papers, 2021 to 2025). A primary or metastatic malignant neoplasm involving the stomach. "Recently, it has been revealed that PAK6 enhances gastric cancer chemoresistance by modulating the DDR." (PMID 40650306, 2025). "In summary, PAK6 emerges as a novel modulator of DDR and chemoresistance in gastric cancer through its activation of the ATR-CHK1-RAD51 repair pathway." (PMID 40869030, 2025). "Another study indicated p21 (RAC1) activated kinase 6 (PAK6) as a critical regulator of the DDR and chemoresistance in gastric cancer, particularly in relation to oxaliplatin, another commonly used bifunctional alkylating agent." (PMID 40869030, 2025). "PAK6 has been proven to promote homologous recombination, enhancing chemoresistance to oxaliplatin through ATR/CHK1 signalling in gastric cancer." (PMID 39233332, 2024).
chronic myeloid leukemia (4 papers, 2022 to 2025). "It is also associated with P21 (RAC1)-activated kinase 6 (PAK6), inhibition of which has been shown to sensitize therapy-resistant cells to tyrosine kinase inhibitors in chronic myeloid leukemia by disrupting the RAS/MAPK pathway and mitochondrial activity." (PMID 39218897, 2024). "Pharmacological inhibition of PAK6 perturbs the RAS/MAPK pathway and mitochondrial activity, sensitising therapy‐resistant leukaemic stem cells in chronic myeloid leukaemia to tyrosine kinase inhibitors." (PMID 39233332, 2024).
melanoma (4 papers, 2013 to 2025). A malignant, usually aggressive tumor composed of atypical, neoplastic melanocytes. "We show that PAK6 kinase activity is regulated by its N-terminal pseudosubstrate in vitro and that a melanoma-associated mutation, P52L, in the pseudosubstrate sequence displays reduced inhibition." (PMID 24204982, 2013). "PAK6 has also been found to acquire somatic mutations in other solid tumors, including mutation of residue Pro52 to leucine in two independent melanomas." (PMID 24204982, 2013). "Introduction of a melanoma-associated mutation, P52L, into this peptide reduces pseudosubstrate autoinhibition of PAK6, and increases phosphorylation of its substrate PACSIN1 (Syndapin I) in cells." (PMID 24204982, 2013). "We find that PACSIN1 shows significantly increased phosphorylation when co-transfected with the P52L mutant compared to the wild-type PAK6, suggesting that the melanoma-associated mutation indeed functions to increase kinase activity." (PMID 24204982, 2013). "Somatic acquired PAK6 point mutations have been discovered in cancer, and interestingly, a recurrent PAK6 mutation that has been observed in two independent melanomas occurs by substituting residue P52 within the pseudosubstrate autoinhibitory region with a leucine." (PMID 24204982, 2013). "We therefore analysed the effect of silencing PAK4 and PAK6 expression on migration of melanoma cells." (PMID 35969127, 2022). "In multiple cancers including melanomas PAK5 most frequently carries non-synonymous mutations; PAK6 and PAK4 have fewer; and PAK4 is often amplified." (PMID 35969127, 2022). "SBcl2 melanoma cells carrying the NRASQ61K mutation are invasive, and the effects of knocking down PAK4 and PAK6 on their migration was analysed using a Transwell Matrigel migration assay." (PMID 35969127, 2022). "PAK4 and PAK6 are expressed to different levels in different melanoma cell lines, while PAK5 expression is low or undetectable in these cells." (PMID 35969127, 2022). "In the genomes of specific cancers, namely breast, head-and-neck, liver, lung adenocarcinoma, squamous cell lung cancer, and melanomas, PAK5 frequently carries non-synonymous point mutations, and small insertions and deletions; PAK6 and PAK4 have fewer; and PAK4 is often amplified." (PMID 35969127, 2022). "To investigate this hypothesis, here we compare the cellular regulation of PAK4, PAK5 and PAK6, and investigate their relative roles in melanoma cells." (PMID 35969127, 2022). "This suggests that the P52L mutant of PAK6 may result in significant reduction of PAK6 autoinhibition in these melanoma tumors, and residual inhibition by the P52L substituted peptide in vitro may be attributable to weak, non-specific interactions." (PMID 24204982, 2013). "Risk forest plot analysis revealed that SFN, PLA2G4E, SERPINB5, WWC1, PAK6, and TEAD3 were the most influential genes in promoting melanoma malignancy." (PMID 41034991, 2025). "Together these genomic, biochemical and cellular data suggest that the oncogenic properties of PAK4 are regulated by PKC–PKD signalling in melanoma, while PAK5 and PAK6 are dispensable in this cancer." (PMID 35969127, 2022). "Together these findings indicate that only PAK4, but not PAK5 and PAK6, can complement the requirement for survival and migration of melanoma cells." (PMID 35969127, 2022).
lung carcinoma (3 papers, 2016 to 2025). "Correlation analysis revealed a positive association between PAK6 and variables such as gender, VA (Veteran’s Administration Lung Cancer Study Group) stage, age, smoking status, CEA, CA19-9, NSE, and ProGRP." (PMID 40708824, 2025). "To understand if PAK6 mediated signaling in cigarette smoke treated lung cancer cells is AKT dependent or independent, we treated the H358-S cells with AKT inhibitor (LY294002) and group II PAK inhibitor (PF-3758309)." (PMID 27542207, 2016). "Our findings indicate that PAK6 plays a crucial role in both proliferation and metastatic potential of lung cancer cells in response to cigarette smoke." (PMID 27542207, 2016). "Several studies have reported overexpression of PAK6 in multiple cancers; however its role in lung cancer is poorly understood." (PMID 27542207, 2016). "Our findings further highlight the need for systematic investigation of PAK6 as a potential therapeutic target for lung cancer in a larger cohort of patients." (PMID 27542207, 2016). "Our results indicate that PAK6 is activated in lung cancer cells in response to cigarette smoke and targeting PAK6 leads to a decrease in oncogenic potential of NSCLC cells." (PMID 27542207, 2016). "Having observed that PAK6 is activated in H358-S cells and that its signaling is modulated by AKT, we next studied the functional significance of PAK6 in lung cancer." (PMID 27542207, 2016). "However, there is no report on the expression of PAK6 in lung cancer." (PMID 27542207, 2016).
Alzheimer disease (2 papers, 2021 to 2024). A progressive, neurodegenerative disease characterized by loss of function and death of nerve cells in several areas of the brain leading to loss of cognitive function such as memory and language. "For miR‐328‐5p, Gys1 (AMPK signaling pathway), Nos1 (Alzheimer's disease) and Pak6 (ErbB signaling pathway) were identified." (PMID 39317458, 2024).
cardiac hypertrophy (2 papers, 2022 to 2023). "Circ_0001006 was demonstrated to sponge the miR-214-3p/PAK6 axis to perform its promoted effect on the development of cardiac hypertrophy." (PMID 37194024, 2023). "Our current results have provided proof to sustain the viewpoint that miR-214-3p suppresses cardiac hypertrophy by repressing PAK6." (PMID 35306484, 2022). "Then, PAK6 inhibited the anti-hypertrophy effect of miR-214-3p in cardiomyocytes, the conclusion showing that PAK6 participated in miR-214-3p-mediated cardiac hypertrophy progress." (PMID 35306484, 2022). "Together, these data suggest that circ_0001006 promoted cardiac hypertrophy via suppressing miR-214-3p targeting to PAK6." (PMID 35306484, 2022). "The present study revealed that circ_0001006 could induce cardiac hypertrophy via inhibiting miR-214-3p binding to PAK6." (PMID 35306484, 2022). "In conclusion, our research demonstrated that circ_0001006 could promote cardiac hypertrophy by decreasing miR-214-3p via targeting PAK6, which is a novel mechanism in cardiac hypertrophy." (PMID 35306484, 2022). "Here, we performed that circ_0001006 was induced in cardiac hypertrophy mice and Ang II-treated cardiomyocytes, which displayed pro-hypertrophy effect by inhibiting miR-214-3p and demonstrated a mechanism of circ_0001006 via the miR-214-3p/PAK6 axis." (PMID 35306484, 2022).
clear cell renal cell carcinoma (2 papers, 2021 to 2023). "PAK4, PAK5, and PAK6 are homologs of CLA4, and PAK6 has also been implicated in clear cell renal cell carcinoma." (PMID 36598488, 2023).
diabetic nephropathy (2 papers, 2023 to 2025). "PAK6 and EGFR, which are significantly more abundant in the uEVs of patients with diabetic nephropathy than in those of healthy controls and patients with T2DM, may be biomarkers for diagnosing diabetic nephropathy." (PMID 40873806, 2025).
esophageal squamous cell carcinoma (2 papers, 2022 to 2025). Esophageal squamous cell carcinoma (ESCC) is a type of esophageal carcinoma (EC) that can affect any part of the esophagus, but is usually located in the upper or middle third. "Acting as a “molecular sponge,” LINC00680 adsorbs miR-423-5p to modulate the expression of PAK6 in esophageal squamous cell carcinoma (ESCC)." (PMID 40223929, 2025).
pancreatic cancer (2 papers, 2015 to 2025). "Upregulation of PAK6 has previously been verified in primary and metastatic pancreatic cancer, and has been shown to be further increased in tumors that relapse after androgen deprivation therapy." (PMID 25426562, 2015). "Interestingly, in pancreatic cancer, PAK4 exhibited the highest frequency of alterations (10%), a notable increase compared to PAK2 (4%) and PAK3 (1%), while PAK1, PAK5, and PAK6 were altered in fewer than 1% of cases." (PMID 39756822, 2025). "There is not enough supporting literature on PAK5 and PAK6 in pancreatic cancer, but the data suggests that these PAK isoforms may play important roles in cellular differentiation and apoptosis." (PMID 39756822, 2025).
squamous cell carcinoma (2 papers, 2015 to 2016). A carcinoma arising from squamous epithelial cells. "We next studied the expression of PAK6 in primary lung tissue (adenocarcinoma and squamous cell carcinoma) using immunohistochemical staining." (PMID 27542207, 2016).
Anxiety (1 paper, 2021). Intense feelings of nervousness, tension, or panic often arise in response to interpersonal stresses. "Further studies with PAK proteins in mice correlated PAK1, but not PAK5 and PAK6, with anxiety-related phenotypes." (PMID 34125184, 2021).
breast tumors (1 paper, 2024). "Accordingly, several lines of evidence indicate that PAK6 is overexpressed in advanced cancers including prostate, colon and breast tumors." (PMID 39419978, 2024).
Epileptic encephalopathy (1 paper, 2022). A condition in which epileptiform abnormalities are believed to contribute to the progressive disturbance in cerebral function. "In addition, the variant seems to overlap with an active promoter region encoding for the readthrough transcripts of BUB1B-PAK6 gene, which product is the same as the downstream gene (PAK6) and was considered as a candidate gene for epileptic encephalopathy." (PMID 35804254, 2022).
leukemia (1 paper, 2025). A malignant (clonal) hematologic disorder, involving hematopoietic stem cells and characterized by the presence of primitive or atypical myeloid or lymphoid cells in the bone marrow and the blood. "Overall, our findings indicate that PAK6 knockdown induces G2-M cell cycle arrest in CML cells, suggesting that PAK6 facilitates leukemia growth by dysregulating cell cycle checkpoints." (PMID 40650306, 2025).
memory impairment (1 paper, 2013). "This suggests that both the Pak5 gene and the Pak6 gene need to be knocked out for learning and memory impairments." (PMID 23593460, 2013).